KRAS (KRas proto-oncogene, GTPase)
Diseases named in the same sentence as KRAS in open-access papers (continued):
Sharing a sentence is not in itself a finding about the gene and the disease.
tumor (continued). "Analysis of five LADC cases of never-smokers without EGFR/KRAS/ALK alterations using transcriptome sequencing identified 56 reads overriding the in-frame EZR-ROS1 gene fusion point connecting EZR exon 10 to ROS1 exon 34 in one tumor." (PMID 23418494, 2013). "Since activation or overexpression of upstream factors like KRAS or BRAF can lead to constitutive activation of ERK, this may in turn activate downstream protein kinases or transcription factors that are likely to enhance tumor development." (PMID 23644885, 2013). "For example, in cell cultures, the V600E mutation increases BRAF activity independent of KRAS and shows lower transforming activity, while inhibition of MEK with small molecules prevents tumor growth in BRAF-mutant tumor xenografts but not in KRAS-mutant counterparts." (PMID 24367680, 2013). "The effect of anti-EGFR therapy depends on whether the tumor has a KRAS mutation; anti-EGFR therapy is not effective for patients with a mutation in codon 12 or 13 of KRAS." (PMID 24040099, 2013). "No cases of concurrent presence of KRAS and EGFR mutations were observed in the same tumor sample." (PMID 23817662, 2013). "It will be therefore interesting to investigate how GAPDH could contribute with FDG uptake level and tumor stage in building a composite prognostic marker, possibly also correlating it with the status of known NSCLC oncogenic genes (PI3K, EGFR, KRAS, ALK, etc.)." (PMID 23988223, 2013). "However, their role was revolutionised by the discovery that patients whose tumours harbour mutant forms of KRAS do not respond to anti-EGFR therapy." (PMID 23356214, 2013). "We present here the final results of the irinotecan versus IrPan comparison for patients with KRAS wild-type tumours who had not received previous anti-EGFR therapy; findings from the irinotecan versus irinotecan plus ciclosporin comparison will be reported elsewhere." (PMID 23725851, 2013). "Our data, together with previously published data, may also suggest that everolimus exerts an antiangiogenic effect, which could mean that tumor KRAS genotype may not preclude a patient from benefiting from everolimus therapy." (PMID 23520486, 2013). "For instance, it has been clarified that ligands of VDAC proteins selectively induce non-apoptotic cell death in tumor cells harbouring mutations in the oncogenes HRAS, KRAS, or BRAF by comparing the binding proteins of erastin A6 and erastin B2, an erastin analogue that lacks its activity." (PMID 23431365, 2013). "The prognostic relevance of the KRAS genotype can be assessed by evaluation of clinical outcome (progression-free survival (PFS), overall survival (OS)) in wild-type and mutant pts, depending on differential tumor biological aggressiveness and predictive effectiveness of treatment strategies." (PMID 23497191, 2013). "Among the 175 patients with MT KRAS tumours, 37 (21.1%) received no further treatment, 23 (13.1%)." (PMID 23174912, 2012). "KRAS is the member of the RAS gene family mostly mutated in CRC; unlike the BRAF mutations, the KRAS mutations have been found to be equally distributed in all tumours, regardless of their MSI status." (PMID 22931052, 2012). "This trend was not present in patients with a wild-type KRAS tumour." (PMID 22804917, 2012). "However, clinical decision making based upon very low prevalence KRAS mutations is controversial, as it has not yet been clarified how mutation heterogeneity within CRC tumours affects outcome in patients treated with EGFR antibodies." (PMID 23173730, 2012). "The hazard ratio for PFS was not influenced by miR-143 expression in wild-type KRAS tumours." (PMID 22804917, 2012). "AURKA-CN level did not affect outcomes among patients with KRAS mutant tumours." (PMID 22240781, 2012).
tumor (continued). "We conclude that EBUS-TBNA of mediastinal lymph nodes infiltrated by NSCLC can provide sufficient tumour material for EGFR and KRAS mutation analysis in the great majority of patients without the need to resort to more invasive surgical mediastinoscopy or mediastinotomy." (PMID 21949883, 2011). "However, not all patients with KRAS WT tumours benefit from anti-EGFR moAbs treatment, meaning that additional genetic determinants of resistance exist." (PMID 21283802, 2011). "A number of LMP tumours lacking KRAS or BRAF mutations harboured genomic aberrations, indicating that different initiating events may be present in these tumours." (PMID 22163003, 2011). "Thus a tumor with a KRAS mutation generally does not also harbor a BRAF mutation, as KRAS is upstream of BRAF in the same pathway." (PMID 21092299, 2010). "A comparable number of tumors from young (<50 years) and old patients (>70 years) was quadruple negative for the four predictive gene markers (KRAS-BRAF-PIK3CA-PTEN); however, 16% of young versus only 1% of the old patients had tumor mutations in PTEN/PIK3CA exclusively." (PMID 21103049, 2010). "Although a previous study reported worse outcomes in patients with early (stages II–III) PIK3CA-mutant CRC, the aggregate data do not currently suggest that KRAS- or PIK3CA-mutant tumours have distinctive clinical profiles or differential response to currently approved chemotherapy." (PMID 19603024, 2009). "These relatively rare mutations, as well as codons 12 and 13 mutations, are responsible for the oncogenic constitutive activation of RAS/RAF/MAPKs pathway and they might account for up to a 10% of resistant patients bearing KRAS codons 12 and 13 and BRAF wild-type tumours." (PMID 19603018, 2009). "Moreover, KRAS‐driven tumours may compensate for the lack of PTP4A1–3 activity by increasing RAS and PI3K signalling, coupled with autophagy addiction." (PMID 40657934, 2025). "However, the overall tumor grade did not correlate with mutant KRAS allelic frequency." (PMID 39906959, 2025). "Furthermore, EGFRm circulating tumor DNA (ct-DNA) clearance on treatment (around cycle 3/4) predicted longer PFS in patients with detectable baseline ctDNA, while nearly half of the patients developed acquired resistance, mainly involving MET, EGFR, and KRAS alterations." (PMID 40725428, 2025). "In addition, studies have shown that inhibition of casein kinase 2 (CK2) may affect metabolic pathways in KRAS mutant CCA, providing a new research direction for targeting KRAS-driven tumor metabolism and is expected to provide a potential new approach for the treatment of CCA." (PMID 40673275, 2025). "Additionally, other biomarkers—including driver mutations (e.g., KRAS/BRAF), immune cell infiltration, and tumor microenvironment features—were not evaluated but may further elucidate response heterogeneity." (PMID 40255436, 2025). "Moreover, important molecular markers, such as KRAS, NRAS, and BRAF mutations, could not be evaluated, thereby restricting the ability to analyze the impact of tumor biology on survival comprehensively." (PMID 41517497, 2025). "Thus, while KRAS G12C inhibitors represent a significant milestone in precision oncology, their impact on OSCC is currently limited, emphasizing the need for more precise molecular profiling to uncover new therapeutic vulnerabilities within the RAS signaling axis in this tumor type." (PMID 40427514, 2025). "Gene ontology (GO) analysis of the Cluster 13 signature revealed a significant enrichment in epithelial-to-mesenchymal transition (EMT) and KRAS signaling gene sets suggesting that Cluster 13 cells have more aggressive metastatic potential compared to non-Cluster 13 cells within the same tumor." (PMID 40527915, 2025).
tumor (continued). "CXCR2 ligands such as CXCL1, CXCL2, CXCL3, and CXCL5 are highly expressed in the tumor microenvironment of KRAS-mutant preclinical models, although their elevated secretion is often attributed to stromal or immune cells rather than direct production by KRAS-mutant tumor cells." (PMID 40524071, 2025). "However, KRAS-mutant tumours do not appear to require as much copy number activity to progress." (PMID 41509216, 2025). "Therefore, KRAS A146-driven cancers may be sensitive to Son of Sevenless protein 1 (SOS1) inhibitors, combined with a MEK-inhibitor, or with SHP2, thus reinforcing the role of MEK inhibition in these tumours even in the current drug development scenario." (PMID 38261067, 2024). "The two-tailed Fisher exact test was used to test the null hypothesis that the variable of the mutational state of the KRAS or NRAS gene was independent of the following clinical-histopathological variables: sex, age, tumor location, stage and degree of tumor differentiation." (PMID 39816392, 2024). "In addition, the heterogeneity of KRAS‐mutant cancers leads to limited efficacy of KRAS inhibitors (KRASi) as monotherapy; while their combination with other targeted agents, including SHP2, EGFR, PD‐L1, CDK4/6, PLK1, and IRE1α, significantly enhances anti‐tumor activity and overcomes resistance." (PMID 39254172, 2024). "In addition, if CCDC6 is mutated or downregulated, the lack of genomic stability might indirectly enhance KRAS-driven oncogenesis by promoting a permissive environment for tumor growth." (PMID 39684377, 2024). "From the perspective of the clinical and pathological characteristics of tumours, the selection criteria could be improved by studying patients presenting similar dissemination patterns or more specific tumour molecular profiles (e.g.: either KRAS positive or negative tumours)." (PMID 38484556, 2024). "Importantly, our established tumor models and patient data reveal that in advanced disease, differences in KRAS mutant isoform-specific potency are no longer evident, mirroring findings from previous large cohort studies which failed to support KRAS-mutant allele-specific differences in outcomes." (PMID 39533328, 2024). "Genomic markers (MSI and BRAFV600E) and tumor microenvironment markers (cancer-associated fibroblasts and cytotoxic lymphocytes) showed similar subtype associations in the cCMS and original CMS frameworks, with the exception that KRAS mutations were not skewed among cCMS classes." (PMID 38773143, 2024). "Moreover, treated with another covalent inhibitor of KRAS-G12C ARS1620, the KRAS-G12C mutant cell would present ARS1620-modified peptides in MHC-I complexes, which could serve as tumor-specific neoantigens to elicit a cytotoxic T cell response against KRAS-G12C cells." (PMID 37110848, 2023). "In addition, KRAS is a new variable and was not routinely recorded, so it may have been incompletely captured by tumor registrars." (PMID 38032636, 2023). "As for the role of KRAS mutation in the effectiveness of anti-VEGF therapy in mCRC patients, a study has shown that tumor KRAS status could not predict treatment response or affect overall survival (OS) of mCRC patients receiving bevacizumab in combination with oxaliplatin-based regimens." (PMID 37511664, 2023).
tumor (continued). "We found that KRAS is substantially correlated with tumor immune cell infiltration, including B cells, CD8+T cells, CD4+T cells, macrophages, neutrophils, and dendritic cells, suggesting that KRAS may affect tumor processing and prognosis through cancer immunity." (PMID 35563733, 2022). "It is considered to activate KRAS transcription and may induce the expression of the proto-oncogene MYB, participating in facilitating aerobic glycolysis and other functions and is therefore involved in the tumor progression and metastasis of several cancer types." (PMID 35988113, 2022). "However, sequence analysis of KRAS or BRAF genes in different pathological regions revealed no oncogenic mutations, suggesting that these mutations may not contribute to tumor progression in Japanese cases of LGSOCs." (PMID 35326657, 2022). "The compound showed similar tumor-suppressive effects on these two cell lines, as shown by its effects on cell viability, suggesting that DXI could inhibit cell growth regardless of KRAS mutation." (PMID 35546148, 2022). "Additionally, KRAS is an established marker of a negative prognosis in patients with primary and metastatic CRC, and the upregulation of HOXB9 in KRAS mutant samples indicates its potential association with aggressive tumour biology." (PMID 35216396, 2022). "Furthermore, a lower level of PD-L1 expression and tumor mutation burden (TMB) in KRAS G12D has also emerged in a more recent study (PD-L1 tumor proportion score KRAS G12D vs. non G-12D: 1% vs. 5%, p < 0.01; TMB G12D vs. non-G12D: median 8.4 versus 9.9 mt/Mb, p < 0.0001)." (PMID 36358848, 2022). "Also, individualizing organoid culture media to target driver mutations in the patient tumor genetic profile, such as EGF-depleted media to enrich for KRAS mutants, may increase PDO formation and eliminate nontumor “contaminants” that may inhibit PDO growth." (PMID 36256477, 2022). "It is possible that a subset of samples could have KRAS mutations not picked up by ctDNA analysis due to lower tumor shedding, as measured by circulating tumor fraction (CTF), the percentage of cell-free DNA that is derived from tumor cells in a blood sample." (PMID 36028483, 2022). "Moreover, genetic ablation of ATG5 in a KRAS-driven mouse model of PDAC enhances the metastatic potential of tumor stem cells, implying an anti-metastatic effect of autophagy under certain circumstances, especially during the initial stages of tumor development." (PMID 36505808, 2022). "There was a ~ three-fold increase in IFNγ secretion, a marker of tumor-specific T cell priming and activity, when splenocytes collected from the cured mice were stimulated by the two KRAS-mutant tumor cell lines, but no IFNγ induction was observed in the non-KRAS-mutant cell line." (PMID 35045886, 2022). "Furthermore, analyzing a subset of patients with PD-L1 tumor proportion score (TPS) ≥ 50% and concomitant gene alterations (n = 8), we found that n = 3 (37.5%) of these patients feature clinical benefit with ICIs administration, despite the presence of a concomitant KRAS gene alteration." (PMID 35955681, 2022). "Thus, the population of tumor cells is in a non-uniform rate of inactive to active KRAS G12C cycling, and cells with KRAS G12C in the active conformation would be insensitive and could reactivate MAPK signaling pathway." (PMID 35267628, 2022). "Therefore, our study aimed to explore the regulatory factors and mechanisms of KRAS mutant LUAD from the perspective of blocking the Ras signaling pathway and antagonizing relevant influencing molecules, explore new therapeutic targets and provide new guidance for targeted tumor therapies." (PMID 36505791, 2022).
tumor (continued). "The presence of these AXL-positive cells was not restricted to tumor-derived cell lines harboring EGFR-oncogenic mutations, as we observed that a similar percentage of AXL-positive cells were present also in cell lines driven for example by mutant KRAS (i.e., A549)." (PMID 34254585, 2021). "Likewise, the correlation between KRAS and glycolysis was further reinforced by immunostaining analysis in CRC tissues, which revealed that tumors with mutant KRAS had a higher expression of tumor glycolytic enzymes, including GLUT1, GLUT3, and HK2, than the tumors with wild-type KRAS." (PMID 33833221, 2021). "No genetic alteration, including KRAS-mutant allele frequency or STK11 mutation status, was able to predict the anti-tumour activity, although baseline gene/protein expression of members of the HER family of receptor tyrosine kinase did exhibit a trend with the degree of anti-tumour response." (PMID 33466360, 2021). "Interestingly, these transcripts were not elevated in Nkx2-1 deleted KRAS-driven tumor cells and decreased cAMP-dependent PKA activity may be one reason why tumor initiation is impaired in BPN tumors." (PMID 33821796, 2021). "Interestingly, the mechanism of action of the MEK inhibitor can determine the different efficacy between KRAS- and BRAF-mutant tumours; specifically, MEK inhibition that also blocks feedback reactivation of MEK by wild-type RAS enhanced efficacy in RAS-mutant tumours relative to BRAF-mutant tumours." (PMID 34200676, 2021). "Therefore, a cell with mutated KRAS will persist to allow succeeding genetic events to promote tumor progression, which could be an explanation as for why we did not notice statistically significant changes in the KRAS gene expression." (PMID 33549031, 2021). "The non-neoplastic cells in the tumor microenvironment interact with tumor cells, creating a complex onco-inflammatory signaling network that enhances the resilience of cancer cells and potentially explaining why targeting KRAS effectors is clinically ineffective." (PMID 34771644, 2021). "Thus, it is not cost-effective for routine determination of KRAS in a tumor sample." (PMID 33114622, 2020). "Thus, the detection of tumor mutations through the BL, contribute to the monitoring of the disease and determine the response to treatment as is the case of anti-EGFR therapy in which only patients with the KRAS gene without mutations respond." (PMID 32629823, 2020). "Hence amplifying oncogenic KRAS spreading via TNT mediated translocation may have important consequences for tumor progression, implying that TNTs have the potential to reprogram malignant cells and alter cells in the tumor environment." (PMID 32244839, 2020). "This might indicate that either previous experiments done with single ions at higher HZE doses did not capture the dose-dependent trend in tissues, or when considering the full spectrum of ions at lower doses KRAS might not be the key driver in inducing tumor growth." (PMID 32045996, 2020). "Nine hallmarks could be related to tumor immunology and collectively showed a decreased expression over time (allograft rejection, complement, IL2-STAT5 signaling, IL-6-JAK-STAT3 signaling, inflammatory response, IFN-α response, IFN-γ response, KRAS signaling up, and TNF-α signaling via NF-κB)." (PMID 31921184, 2019). "Importantly, the prognostic significance of IL12B was further strengthened by its ability to stratify within many currently known prognosticators, including gender (female), age at diagnosis (>65 for OS), tumor stage I, with EGFR mutation, and without KRAS mutation." (PMID 31004093, 2019).